MMP9 (matrix metallopeptidase 9)
Diseases named in the same sentence as MMP9 in open-access papers (continued):
Sharing a sentence is not in itself a finding about the gene and the disease.
tumor (continued). "Infiltrating neutrophils continue to promote tumor development by secreting pro-inflammatory and pro-angiogenic chemokines and cytokines, such as matrix metallopeptidase 9 (MMP9) and interleukin 6 (IL-6)." (PMID 34503307, 2021). "Aside from these direct effects on angiogenesis, CAFs have also been shown in numerous studies to indirectly affect tumor growth from the ECM through expression of MMPs such as MMP9 and MMP13." (PMID 33808627, 2021). "The Fc-tamed antibodies can be activated by a tumor-specific protease (MMP-9), displaying recovered ability to interact with complement components and FcγR-bearing cells." (PMID 34413859, 2021). "On the contrary, NK cells representing a CD56brightCD16+ subset can facilitate tumor development by releasing the matrix metalloproteinase 9 (MMP9) and secreting the vascular endothelial growth factor (VEGF) and angiogenin." (PMID 34885122, 2021). "TGF-β-induced tumor invasion and metastasis are closely related to the proteolytic activity of MMP-9." (PMID 34769032, 2021). "This treatment suppressed primary tumor growth and inhibited lung metastasis formation in 4T1 tumor-bearing mice as a result of matrix metalloproteinase-9 (MMP)-9 and Bcl-2 level downregulation as well as E-cadherin upregulation." (PMID 34884550, 2021). "The tumor cell region in the CAL27/MMP-9/shRNA or SCC15/MMP-9/shRNA cell group was reduced compared to that in the control group as shown by H&E staining." (PMID 33828938, 2021). "These factors promote ECM degradation and modulation by secreting matrix metalloproteins (MMPs) such as MMP-2 and MMP-9 for effective invasion and metastasis of tumor cells." (PMID 33925575, 2021). "MMP9 participates in the invasion of tumor cells via promoting the degradation of extracellular matrix proteins including the basement membrane and the surrounding stroma." (PMID 33858512, 2021). "Analyses of whole lungs confirmed the increased expression of Bv8 and Mmp9 upon deletion of Junb specifically in tumor-bearing mice." (PMID 34282521, 2021). "MMP-9 serves a critical function in tumor angiogenesis by modulating growth plate angiogenesis and endothelial stem cell recruitment." (PMID 33762939, 2021). "We further discovered that the protein levels of MMP9 were decreased after GAPLINC knockdown in the tumor tissues of nude mice." (PMID 34722262, 2021). "Among these, MMP-2 and MMP-9 are of particular relevance since they are usually overexpressed in tumor cells and are capable of degrading type IV collagen of basement membrane, the first barrier for cancer invasion." (PMID 34202184, 2021). "Previous studies have shown that MMP-9 inhibition promotes anti-tumor immunity through trafficking of T cells to the tumor." (PMID 34038440, 2021). "MMP9 enables the recruitment of EPC to the tumor vasculature by increasing VEGF mobilization and bioavailability." (PMID 33921099, 2021). "The MMP-9 cleavable coating facilitated nanoparticles satisfactory systemic circulation lifetime and significantly enhanced cellular uptake in tumor." (PMID 34201333, 2021). "MMP-9 modulate cell proliferation, adhesion, apoptosis and differentiation and play an important part in tumor growth, angiogenesis and metastasis." (PMID 33968773, 2021). "MMP-9 plays a crucial role in the early stages of tumor invasion, with the primary function of degrading and remodeling the homeostasis of the ECM." (PMID 33828938, 2021). "Once the nanostructure reaches the tumor area, the gelatin layer of the NPs is degraded by MMP9, leading to the release of imatinib molecules into the gelatin layer and the tumor ECM, respectively." (PMID 34834387, 2021). "An MMP with an important activity in tumor invasion is MMP9, which is expressed in several tumors, including HNSCC." (PMID 34204259, 2021).
tumor (continued). "Platelet microparticles (PMPs) are thought to transfer receptors to the surface of tumor cells through membrane fusion, induce tumor cell chemotaxis, promote tumor cell proliferation, and induce the expression of IL-8, MMP-9, and VEGF." (PMID 34422629, 2021). "Non-anticoagulant heparin derivatives such as SST0001 or roneparstat significantly downregulated heparanase-dependent cleavage of syndecan-1 HS chains, attenuated HGF, VEGF, and MMP-9 expression resulting in decreased tumor growth and angiogenesisinvivo." (PMID 33800172, 2021). "CD8 + T cell-derived exosomes with membrane expression of Fas ligand (FasL) can promote invasion and metastasis of Fas+ tumor cells through matrix metalloproteinase-9 (MMP-9)-mediated degradation of extracellular matrix proteins." (PMID 34266354, 2021). "Macrophages have an inherent ability to navigate desmoplasia-dense tumor regions, a feature that in M2-like macrophages is partly mediated by their high matrix metallopeptidase 9 (MMP-9) activity." (PMID 34041037, 2021). "Meanwhile, tumor invasion and migration ability and the associated genes, including MMP-9 (Matrix metalloproteinase-9) and uPA (Urokinase-type plasminogen activator), were all diminished by treatment with magnolol." (PMID 34947930, 2021). "Previous studies have reported the role of matrix metalloproteinase-2 (MMP-2) and MMP-9 in cancer development, including tumor cell growth, migration, invasion, and metastasis, and particularly so in HCC." (PMID 34048194, 2021). "CD44, a cell-surface glycoprotein involved in cell–cell interactions, cell adhesion, and migration, can interact with MMP9 to promote tumor growth and metastasis." (PMID 34073849, 2021). "Positive expression of MMP-9 is linked with PTX3 expression in lung adenocarcinoma, suggesting an association of PTX3 with tumor grade and severity of malignancies." (PMID 34912809, 2021). "The tumor-promoting genes (Lrp5, MMP9, Runx2 and Snail) in EO771 cells were decreased by treating with Snail-overexpressing MSC CMs and the effect was reversed by silencing Snail." (PMID 33859739, 2021). "Piegeler and colleagues reported that lidocaine reduced tumor cell ability of invasion by repressing MMP-9 formation and release." (PMID 34249706, 2021). "MMP-9 is a peptidase and its activity is to degrade the extracellular matrix and to induce tumor neovascularization during tumor progression and metastasis." (PMID 34833068, 2021). "After GBF1 knockdown, the expression of FAM129A was upregulated, but the MMP9 protein level was decreased, as well as the secretion thereof to the extracellular, which was different from that in tumor cells." (PMID 34513838, 2021). "Due to their capacity to degrade basement membrane components, the gelatinases MMP2 and MMP9 are key molecules for the spreading of tumor and metastatic progression." (PMID 34830271, 2021). "Pre-analysis centrifugation of samples spiked with the T24 tumor cell line reduced levels of MMP9, SDC1, PAI1, ApoE, and ANG." (PMID 34204951, 2021). "On the contrary, the loss of KLF4 weakened the inhibition of N-cadherin, MMP2, and MMP9, leading to increased tumor cell invasion and migration, thereby affecting survival and prognosis." (PMID 34367275, 2021). "MMP-9 (or gelatinase B) belongs to a family of MMPs that are highly expressed in pathological processes including inflammation and tumor invasion." (PMID 33431821, 2021). "Curcumin has been shown to significantly reduce tumor volume, and activity of MMP-2 and MMP-9 at the tumor-bearing site." (PMID 33578780, 2021). "MMP9 is involved in many biological processes and plays roles in tumor progression and invasion, angiogenesis, and determining the composition of the tumor microenvironment." (PMID 34298981, 2021).
tumor (continued). "Tumor cells also express MMP-9 (Matrix Metallopeptidase-9) that allows the dissemination of tumor cells and, at the same time, is essential for the activation of angiogenic factors." (PMID 34830463, 2021). "MMP-9 is a zinc-dependent enzyme present in the extracellular milieu and involved in the regulation of the tumor microenvironment." (PMID 34707964, 2021). "DET abolished TNFα-induced MMP-9 enzyme activity and expression, and NF-κB activation in TS/A tumor cells." (PMID 34948368, 2021). "The NF-κB/MMP-9/VEGF pathway plays pivotal roles in the tumor progression, angiogenesis, and metastasis." (PMID 34059099, 2021). "Tumor-associated MDSCs promote tumor progression by inducing tumor angiogenesis via the release of growth factors, cytokines, and metalloproteinases (e.g., VEGF, Bv8, MMP9) in response to tumor hypoxia and by STAT3 activation in MDSCs." (PMID 34771577, 2021). "MMP9 mainly acts as a collagenase degrading type IV collagen, and is critical for tumour cell growth, migration, invasion, metastasis and angiogenesis." (PMID 33573134, 2021). "The expression levels of tumor progression-related proteins (MMP9, PCNA, and IL-1β) and MDSCs' proliferation and activation-related proteins (COX2 and PDL1) were significantly downregulated." (PMID 34055197, 2021). "Tumor-associated N2 neutrophils are identified by high expression of VEGF, CXCR4, gelatinase B, and MMP9 and can be induced on exposure to high TGF-β levels." (PMID 34660642, 2021). "IHC analysis of MMP9 and E-cadherin showed positivity in the tumor cells of NSCLC patient tissue samples." (PMID 33833996, 2021). "DKK1 enhanced tumor cell invasion and promoted lymph node metastasis through the induction of MMP9 and VEGF-C." (PMID 34093545, 2021). "We recently demonstrated that mast cells (MCs) can favor the growth of prostate adenocarcinoma, providing MMP9 at initial stages and inhibiting the anti-tumor immune response." (PMID 33737929, 2021). "Cytochalasin D has been shown to block the expression of CD44, the major MMP-9 docking site on the surface of various tumor cells and primary keratinocytes." (PMID 33807594, 2021). "MMP9 and two lncRNAs (MIR4435-2HG and DUXAP8) were highly expressed in HCC and were associated with a poor prognosis in patients with HCC and with immune tumor cell infiltration." (PMID 35201491, 2021). "MMP-9 expression and activity in tumors and in TAMs increase during tumor progression of the Rip1-Tag2 cancer model." (PMID 33783686, 2021). "IL33 also greatly contributes to angiogenesis through the recruitment and activation of not only immunosuppressive ST2+ MDSCs that produce VEGF, FGF, and MMP9 but also inflammatory ST2+ cells, including tumor-associated macrophages (TAM) and mast cells." (PMID 33535613, 2021). "Stimulation of macrophages with IL‐33 markedly increases MMP‐9 production, which remodels the extracellular components to facilitate tumor invasion." (PMID 34486239, 2021). "In contrast, N2 has tumor-promoting activity, promoting angiogenesis and inhibiting the function of NK cells by releasing matrix metalloproteinase 9 (MMP9)." (PMID 34447376, 2021). "MMP‐9 plays a crucial role in tumor progression, from angiogenesis, to stromal and bone remodeling, and ultimately to metastasis." (PMID 32985799, 2021). "Quantification analysis revealed that the knockdown of MMP-9 decreased the average metastatic distance and number of metastatic tumor cells or lesions at 5 dpi." (PMID 32382550, 2020). "We found further that Calebin A significantly suppressed TNF-β-induced phosphorylation and nuclear translocation of p65-NF-κB, similar to BMS-345541 (specific IKK inhibitor) and NF-κB-induced tumor-promoting biomarkers (NF-κB, β1-Integrin, MMP-9, CXCR4, Ki67)." (PMID 32244288, 2020). "RT-PCR analysis showed that the mRNA levels of Bv8, S100a8, S100a9, and Mmp9 were significantly higher in the lungs of tumor-bearing mice after 2 weeks of sunitinib treatment than those in tumor-bearing control mice." (PMID 32993785, 2020).
tumor (continued). "We found that tumours of ibrutinib-treated mice expressed significantly lower transcripts of Vegf, Mmp9, and Cxcl1 compared to tumours of the vehicle-treated group." (PMID 32025027, 2020). "Removing the MAPK7/MMP9 signalling axis by RNA interference suppressed tumour burden, metastatic spread and increased overall survival in animals by inhibition of TAM infiltration." (PMID 32655131, 2020). "ADAMTS-1 is anti-angiogenic, whereas MMP9 is highly pro-angiogenic, and can trigger the ‘angiogenic switch’, a process in tumours where the balance of pro- and anti-angiogenic factors swings towards a pro-angiogenic outcome." (PMID 32269093, 2020). "Another research invented an exogenously administered tumor-penetrating nanosensor, which sheds peptide fragments, detected in the urine, in response to a tumor-specific protease, MMP9." (PMID 32377504, 2020). "Tumours expressing high MMP9 mRNA expression showed significantly shorter BCSS than the low expression subgroup (p < 0.0001; HR = 1.5; 95%CI 1.2–1.8)." (PMID 32445177, 2020). "In general, a very weak correlation was found between MMP-2 and MMP-9 levels and survival and tumor volume." (PMID 33126765, 2020). "Here, we have evaluated matrine for its activity on C-X-C chemokine receptor type 4 (CXCR4) and matrix metalloproteinases (MMP-9/2) expression, and its potential to affect tumor metastasis and invasion." (PMID 32630806, 2020). "IGF-1 signals intracellularly through the PI3 and MAPK pathways after binding to IGF-1R on the cell surface, and IGF-1 thereby increases the enzymatic activity of MMP-2 and MMP-9 and enhances the proliferation and migration of tumor cells." (PMID 32972437, 2020). "Several studies have shown that CD147 and MMP-9 are related to the development, invasion, and metastasis of tumor cells." (PMID 32377273, 2020). "Simultaneously, MMP-9 can induce tumor angiogenesis by releasing biologically active VEGF from the extracellular matrix of the TME." (PMID 32913278, 2020). "Some experts believe that tumor histology distinction should be considered when interpreting MMP-9 over expression." (PMID 32944046, 2020). "Taken together, these results suggest that the reduction in MMP-9 expression in TAMs is significantly correlated with the inhibition of tumor angiogenesis in the Plasmodium-infected model." (PMID 32972437, 2020). "In our study, greater numbers of lung carcinoma tumors and larger tumors were found in PRDX4 Tg mice, accompanied by enhanced macrophage infiltration and the elevated expression of IL-1β and MMP9 in tumor microenvironment." (PMID 33456675, 2020). "TAMs further support the tumor microenvironment through the secretion of MMP-9 to promote angiogenesis and further tumor progression." (PMID 33050151, 2020). "Studies have shown that MMPs, including MMP-2 and MMP-9, are highly expressed in various tumor cells." (PMID 32259133, 2020). "Matrix metalloproteinase-2 (MMP-2) and MMP-9 have been shown to play important roles in regulating metastasis and the tumor microenvironment." (PMID 32922544, 2020). "The results showed that NWXF can down-regulate the expression of Sp1, MMP2, and MMP9 in tumor tissues." (PMID 33329003, 2020). "In contrast, expression levels of both MMP2 and MMP9 were significantly higher in tumours excised from the aspirin-treated mice." (PMID 32246008, 2020). "It has been shown to upregulate the expression of matrix metalloproteinase 9 (MMP-9), which has been linked to tumor invasion and metastasis." (PMID 32266132, 2020). "It has been found that matrix metalloproteinase 9 (MMP9) secreted by TAMs promotes the migration of tumor cells by promoting the migration of endothelial cells, which promotes angiogenesis." (PMID 33224886, 2020). "MMP9 is a matricellular protein associated with extracellular matrix (ECM) remodelling, that promotes tumour progression, and modulates the activity of cell adhesion molecules and cytokines." (PMID 32445177, 2020).
tumor (continued). "MMP-9, also known as gelatinase B, is an extracellular protease that remodels the tumor environment by degrading the endothelial basement membrane." (PMID 33716731, 2020). "In vivo studies indicated that the codelivery of docetaxel or MMP-9 resulted in enhanced tumor inhibition." (PMID 33333778, 2020). "Targeting MMP9 of tumor infiltrating macrophages by a bisphosphonate, zoledronic acid, inhibited the angiogenesis in a cervical carcinoma model." (PMID 33343560, 2020). "Endogenous interferon-β (IFN-β) has been shown to inhibit angiogenesis by downregulating the proangiogenic factors VEGF and MMP-9 in tumor-infiltrating neutrophils." (PMID 33363012, 2020). "DDR1-IN-1 decreased total MMP2 and total MMP9 (mainly detected as pro-MMPs and active MMPs) secretion by basal HSCs and tumor-activated-HSCs." (PMID 33110221, 2020). "In this study, the expression levels of MMP‐2 and MMP‐9 in transplanted tumor tissues were significantly decreased during the 3‐7 days of low‐dose apatinib treatment compared with those in other groups (P < .05)." (PMID 32073228, 2020). "Different co-culture of CRC cell lines and TAM cell lines cause the upregulation of tumor cell-derived MMP-2 and MMP-9 expression and secretion, with increased tumor invasiveness and migration." (PMID 32984031, 2020). "Some of MMPs including matrix metalloproteinase 2(MMP-2) and matrix metalloproteinase 9(MMP-9) have significant roles in different stages of tumor progression." (PMID 32582823, 2020). "This is consistent with another study which found MMP9 as differentially expressed between molecular subsets of tumours and as a feature of TNBC and HER2 + BCs." (PMID 32445177, 2020). "The difference in pharmacokinetics was assigned to the highest MMP9 level in the A431tumours that led to cleavage of the peptide radiolabeled with 111In and its clearance from the tumour." (PMID 33375074, 2020). "Two types of tumours with different MMP9 expression levels (high = A431; low = 4T1Luc) were implanted in nude mice to explore the ability of the nanoparticles to accumulate in tumours showing MMP9 activity." (PMID 33375074, 2020). "Then, MMP-9 completes the cleavage of interstitial collagens, thereby contributing to cancer cell detachment from the primary tumor mass." (PMID 32630531, 2020). "In TNBC, brucine, a traditional medicinal herb, was reported to inhibit VM formation in a dose-dependent manner, and downregulate the expression of EphA2, MMP-2, and MMP-9, which are key mediators of tumor invasion, metastasis, and VM formation." (PMID 32169087, 2020). "Cases showing low expression of MMP-9 in the tumor and stroma revealed higher survival rates (p = 0.04; p = 0.01)." (PMID 32669083, 2020). "MMP‐9 from tumor and stromal cells, particularly macrophagocytes, has an indispensable position in the invasive, migratory, and angiogenic progression of malignant tumors." (PMID 32720731, 2020). "Another prognostic indicator of poor outcome in cancer patients is MMP-9, which has widely been found to relate to the pathology of cancers, including tumour growth, invasion, metastasis, and angiogenesis." (PMID 33260615, 2020). "They further found that iNOS-derived NO secreted by cancer cells modulates MMP-9 production, thereby contributing to tumor cell angiogenesis, invasion, EMT process and HCC metastasis." (PMID 32414178, 2020). "Principally, using Hyp-PDT prevents tumorigenesis by impeding tumor-promoting cytokines’ signaling and downregulating mediators of tumor metastasis like matrix metalloproteinase-9 (MMP9)." (PMID 32340275, 2020). "Their tumor promoting activity is mediated by an increased production and activation of matrix metalloproteinases, in particular MMP9 and MMP14." (PMID 32331440, 2020). "Matrix‐metalloproteinases (MMPs) (MMP2 and MMP9), closely related to the tumor cell metastasis, were downregulated by EZH2 knockdown." (PMID 31855281, 2020).